PTH (parathyroid hormone)
Diseases named in the same sentence as PTH in open-access papers (continued):
Sharing a sentence is not in itself a finding about the gene and the disease.
metabolic syndrome (continued). "Patients with 25(OH)D level below normal were older and had significantly higher systolic BP, fasting glucose levels, G-120, G-AUC, I-AUC, PTH levels, and prevalence of metabolic syndrome than patients with normal serum 25(OH)D levels." (PMID 35057492, 2022). "In terms of T-score, age, BMI, serum phosphate, parathyroid hormone level, gastrointestinal ulcer history, and dyslipidemia were identified as significant confounding variables." (PMID 35454336, 2022). "The association of parathyroid hormone (PTH) and vitamin D with Metabolic syndrome (MetS) was evaluated using representative data from the Korean population." (PMID 29348466, 2018). "VitD and PTH may also play important roles in cardiovascular risk, which has been suggested to be associated with metabolic syndrome (MetS) and is very prevalent in Portugal." (PMID 29149839, 2017). "Though inconsistent, a number of studies have shown an association between vitamin D (25(OH)D) status, parathyroid hormone (PTH) and the metabolic syndrome (Met S)." (PMID 23596520, 2013). "Multiple regression models for determining the effects of ethnicity, PTH and 25(OH)D on components of the metabolic syndrome." (PMID 23596520, 2013). "However, PTH, in addition to BMI, insulin and metabolic syndrome score, was found to be an independent predictor of leptin values with both, PTH and leptin, correlating positively in patients at different CKD stages." (PMID 36289903, 2022). "Patients with 25(OH)D deficiency/insufficiency were older and had significantly higher blood pressure, fasting and post-OGTT (G-AUC) glucose levels, post-OGTT insulin (I-AUC), PTH levels, and prevalence of metabolic syndrome than patients with normal serum 25(OH)D." (PMID 35057492, 2022). "In addition, the more criteria of the NCEP for metabolic syndrome were met, the higher the parathyroid hormone (PTH) level and ACCA were." (PMID 32081877, 2020). "Moreover, the dyslipidemia consequence of higher PTH level can also be attributed to central obesity." (PMID 32081877, 2020). "The PTH level may also have different influences on bone metabolism and metabolic syndrome among different ethnicities and genders." (PMID 30363962, 2018). "Cox-regression analysis showed that serum bicarbonate levels and interdialytic urine volume were significant risk factors for PVD prevalence adjusted for defined by Kt/V for urea dialysis adequacy, dyslipidemia and defined by i-PTH serum concentrations mineral bone disease." (PMID 28933414, 2016). "However, the age, dyslipidemia, BMI, oxidative status defined by oxLDL, i-PTH and dialysis adequacy determined by kt/V for urea showed significant risk factors." (PMID 29371512, 2015). "Moreover, the correlation study revealed in PHPT patients, a positive correlation between SBP and PTH levels (r = 0.512; P < 0.05) The prevalence of metabolic syndrome was present in 38% of PHPT and in 28% of EH patients." (PMID 22719761, 2012). "PTH was associated with higher odds of atherogenic dyslipidemia in both model 1 and model 2, but not after adjustment for BMI (model 3)." (PMID 23228198, 2012). "Although some evidence has been provided that low serum 25-hydroxyvitamin D (25-OH-D) may be involved in the development of the metabolic syndrome, one has to be aware of several possible confounders like PTH, serum calcium, factors involved in the IGF1 system, physical activity, and social status." (PMID 24026893, 2013). "A controversial association has been reported between low levels of plasma 25(OH)D and/or elevated PTH and the presence of metabolic syndrome (MetS) and its individual components." (PMID 23228198, 2012). "They found a strong correlation between PTH and SBP and a high prevalence of metabolic syndrome, with significant improvements after parathyroid surgery." (PMID 24026893, 2013).
metabolic syndrome (continued). "Thalassemic children have significant growth failure, lower total mean serum calcium, vitamin D, and PTH, high phosphorus levels, ALT and alkaline phosphatase, and dyslipidemia, as compared to controls, which signifies the importance of targeted therapeutic interventions to address this deficiency." (PMID 39233987, 2024). "Higher serum parathyroid hormone (PTH) levels were shown in HD patients with atherogenic dyslipidemia compared with PTH concentrations in HD subjects without this type of dyslipidemia, however, only at the borderline level of significance (P = 0.067)." (PMID 31775661, 2019). "Using the same cohort of adults in greater Johannesburg, elevated PTH, not low 25(OH)D, predicted metabolic syndrome, although 25(OH)D inversely correlated with PTH." (PMID 27763570, 2016). "Addition of the other metabolic syndrome components to the logistic regression model does not attenuate the p-value/OR for PTH and in some cases increases it." (PMID 23596520, 2013). "It has been postulated that, parathyroid hormone mediates the direct effects from phosphate, calcium, vitamin D, and magnesium on metabolic syndrome in women but not men." (PMID 22192330, 2011). "In addition, we did not assess diet, vitamin D supplements, parathyroid hormone levels as well as fasting blood sugar and lipid levels, which are important factors related to circulating serum 25(OH)D and metabolic syndrome." (PMID 38413628, 2024). "The PTH level, but not the vitamin D level, is an independent predictor of metabolic syndrome." (PMID 24782595, 2014).
osteosarcoma (69 papers, 2008 to 2025). A usually aggressive malignant bone-forming mesenchymal neoplasm, predominantly affecting adolescents and young adults. "Parathyroid Hormone Analogs (e.g. teriparatide) promote bone formation but are limited by high cost, short-term use (≤24 months), and potential osteosarcoma risk." (PMID 40844970, 2025). "The 15‐year US Osteosarcoma Surveillance Study was initiated in 2003 to evaluate a potential association between the recombinant human parathyroid hormone analog teriparatide (Forteo; Eli Lilly and Company, Indianapolis, IN, USA) and osteosarcoma in humans." (PMID 32990990, 2021). "This lies in contrast to PTH, whose clinical use is limited by the risk of osteosarcoma as suggested by rat studies." (PMID 26082355, 2015). "Toxicological studies of PTH and its related protein analogs in animals have shown that the lifetime use of PTH and its related protein analogs in excess of equivalent human doses of PTH results in an increased risk of osteosclerosis and osteosarcoma." (PMID 35774616, 2022). "Preclinical evidence shows a potential association between PTH and osteosarcoma." (PMID 35462909, 2022). "PTH has been shown to increase osteosarcoma in rats and may increase the risk of osteosarcoma occurrence in humans." (PMID 29456575, 2017). "We have tested all the human osteosarcoma lines available, and only SaOS-2 cells show any PTH responsiveness, and even that is low." (PMID 40609791, 2025). "Despite the similar use of PTH for the treatment of medication-related osteonecrosis of the jaw (MRONJ), there are still concerns about the risks of PTH-induced osteosarcoma based on the animal studies that reported the development of osteosarcoma in rats." (PMID 39682583, 2024). "High-dose and long-term use of teriparatide, a parathyroid hormone analog, promotes bone formation but increases the incidence of osteosarcoma in rats." (PMID 38019761, 2023). "Studies in isolated bone cell populations and in osteosarcoma cells that are phenotypically osteoblastic, showed repeatedly that as well as PTH, the best characterized bone resorbing factors (e.g. prostaglandins." (PMID 35126319, 2021). "Parathyroid hormone (PTH) is the only Food and Drug Administration-approved agent that stimulates bone formation, but it has been linked to osteosarcoma and can only be used for 2 years." (PMID 32023550, 2020). "Continued parathyroid hormone treatment decreases Dkk-1 mRNA levels in rat osteosarcoma cells in culture." (PMID 31477034, 2019). "Of the 300000 postmenopausal women consumed PTH worldwide, osteogenic sarcoma was reported only in one case." (PMID 30320008, 2018). "PTH-stimulated cAMP content has been reported to be mediated, at least in part, by AC6 in human embryonic kidney and osteoblasts, while PTH-induced increases in endosomal cAMP content in osteosarcoma cells are partly mediated by AC2." (PMID 28882112, 2017). "Using an orthotopic model of canine osteosarcoma in athymic rats, we found combination therapy (ZA/PTH) increased bone volume and polar moment of inertia as compared to SRT alone." (PMID 27332712, 2016). "This work provides further evidence for the expanding potential indications for ZA and PTH therapy, including post-irradiated bone disease due to osteosarcoma." (PMID 27332712, 2016). "Active osteosarcoma was discovered in four subjects (one from each of the following treatment groups: PTH, LPTH, ZA/PTH, SRT Only), but exhibited an average of 85% tumor necrosis." (PMID 27332712, 2016). "Further work is necessary to elucidate the effectiveness of PTH in restoring bone properties following osteolysis due to osteosarcoma and radiation therapy, especially in immunocompetent models." (PMID 27332712, 2016). "Preclinical studies in F344 rats found that a significant percentage of subjects developed osteosarcoma following two years of treatment with PTH." (PMID 27332712, 2016).
osteosarcoma (continued). "A preclinical study found that Fisher 344 rats administered PTH for 2 years had a significantly increased percentage of developing osteosarcoma." (PMID 26441073, 2015). "In rats overdosing of PTH has even led to the formation of osteosarcoma and thus application of PTH in humans is currently limited to two years." (PMID 24312339, 2013). "Further studies are required to determine the prognostic significance of PTH/PTHrP/PTHR1 signalling in osteosarcoma." (PMID 21559216, 2011). "Fischer 344 rats developed high rates of osteosarcoma from prolonged administration of the parathyroid hormone biological analog, even at lower doses." (PMID 21403899, 2011). "Parathyroid hormone (PTH), parathyroid hormone-related peptide (PTHrP), and the receptor (PTHR1) have been implicated in the progression and metastasis of osteosarcoma." (PMID 21559216, 2011). "Although parathyroid hormone (PTH) replacement therapies are becoming available, their widespread use is limited by factors such as high cost, inability to accurately mimic physiological PTH levels, and potential risks like osteosarcoma." (PMID 41329538, 2025). "The use of parathyroid hormone analogues for more than two years is not recommended, as animal models have demonstrated a dose-dependent increase in the risk of osteosarcoma formation." (PMID 41303575, 2025). "The use of parathyroid hormone analogues for more than two years is not recommended due to a dose-dependent increase in the osteosarcoma formation risk in animal models." (PMID 41303575, 2025). "In addition, trials of PTH analogs were shorter than 24 mo due to safety concerns regarding osteosarcoma, based on animal studies." (PMID 39127916, 2024). "Teripapeptide, a derivative of parathyroid hormone, may increase the incidence of bone tumors, such as osteoma, osteoblastoma, and osteosarcoma." (PMID 40226399, 2023). "While preclinical evidence showed a potential association between PTH and osteosarcoma, the most recent clinical data do not show any such relationship between iPTH and malignancy." (PMID 35462909, 2022). "A study in rats found that long-term PTH administration induced osteosarcoma." (PMID 34140410, 2021). "The use of teriparatide in the clinic on patients with cancer is highly improbable as it was shown to increase incidences of osteosarcoma in rodents- but the anti-tumor effects of PTH warrants further investigation into the use of bone anabolic agents against osteolytic breast cancer." (PMID 32117726, 2020). "Parathyroid hormone (PTH) and parathyroid hormone-related peptide (PTHrP) are generally avoided in patients who have undergone radiotherapy for the skeleton due to the association of teriparatide with osteosarcomas in animal models." (PMID 32454821, 2020). "Likewise, TCS downregulated parathyroid hormone- (PTH-) or PGE2-stimulated matrix metalloproteinase-13 (MMP-13) expression in rat osteoblastic osteosarcoma cells." (PMID 31191794, 2019). "UMR-106 cell line was chosen as a model in our study as it was a rat osteosarcoma cell with more mature osteoblastic phenotypes that were commonly used by others for studying the effects of different hormonal agents (PTH, prostaglandins, and bone resorbing steroids) on signal transduction." (PMID 29867480, 2018). "However, the currently prescribed parathyroid hormone (PTH)‐based anabolic drugs present limitations and adverse effects including osteosarcoma during long‐term use." (PMID 26941261, 2016). "Ongoing surveillance of human osteosarcoma patients has not detected a causal association between PTH therapy and osteosarcoma." (PMID 27332712, 2016). "PTH and PTHrP act through PTH receptors to regulate the fate of BMSCs towards osteoblasts or adipocytes in bone and to promote angiogenesis as well, but PTH and PTHrP should not be used for a long time because of the risk of inducing osteosarcoma." (PMID 37576993, 2023).
osteosarcoma (continued). "Replacement therapy with synthetic PTH compounds (PTH1-34, Natpara® and PTH1-84, teriparatide, Forsteo®) has been assessed in multicentre trials, but the use of this medication is restricted by costs and concerns related to the risk of development of osteosarcoma." (PMID 33599211, 2021). "Similarly, PTH treatment was showed to reduce serum sclerostin levels in postmenopausal women that may also lead to osteosarcoma." (PMID 32664215, 2020). "Rationale:There are reports of osteosarcoma in rat models after use of teriparatide (PTH1-34) and full-length PTH." (PMID 36149449, 2022). "For example, parathyroid hormone (PTH) has shown a superior antinociceptive effect on LBP in recent studies, whereas its risk of causing osteosarcoma and Paget’s disease is not negligible." (PMID 37961590, 2024). "Parathyroid hormone (PTH), parathyroid hormone related peptide (PTHrP) and parathyroid hormone receptor (PTHR1) have been shown to be related to the progression and metastasis of osteosarcoma." (PMID 34646831, 2021). "Follow up dose and duration studies discovered that low dose (5 μg/kg) PTH resulted in no neoplastic changes, but high dose (30 μg/kg) PTH administered over 20–24 months (70–80% of lifespan) resulted in significant increases in osteosarcoma incidence." (PMID 27332712, 2016). "However, because carcinogenicity studies in rats have found that PTH induces osteosarcomas, the use of PTH is limited to no more than 2 years." (PMID 28246925, 2017). "There have been no studies of parathyroid hormone in children with OI; there is a “black box” warning against the use of parathyroid hormone and parathyroid hormone-related peptide in children, based on the occurrence of osteosarcomas in growing rats receiving these interventions." (PMID 38553634, 2024).
nephrocalcinosis (68 papers, 2014 to 2026). Nephrocalcinosis is a disorder that occurs when too much calcium is deposited in the kidneys. "Careful vitamin D supplementation and biochemical monitoring of calcium metabolism, including PTH, from the first month of life should support bone health and limit the risk of nephrocalcinosis." (PMID 39768792, 2024). "The patient was scheduled for a follow-up one year later to perform blood and urine analysis to uncover the cause of nephrocalcinosis, displaying high serum calcium and parathyroid hormone (PTH) levels." (PMID 38146580, 2023). "Serum calcium, phosphate, ALP and PTH levels should be intermittently monitored and regular urine calcium excretion and renal ultrasonography are suggested because of the risk of nephrocalcinosis." (PMID 29280738, 2017). "Phytate in the AIN-96-G diet caused a dramatic time- and concentration-dependent increase in PTH levels, leading to PTH-induced impairment of the renal reabsorption of Ca2+ and phosphate, and predisposed rats to the development of hypophosphatemic rickets and nephrocalcinosis." (PMID 32271147, 2020). "Additional studies are necessary to determine the impact of TransCon PTH on events such as nephrocalcinosis and the development of renal dysfunction." (PMID 39376010, 2025). "Upon further investigation at our institution, the patient was found to have elevated serum calcium levels, nephrocalcinosis on ultrasound, and an extremely high parathyroid hormone level (2810 pg/ml), which directed attention toward a parathyroid disorder." (PMID 39822449, 2024). "Noteworthily, an inverse trend of probability of nephrocalcinosis in this group was observed when PTH levels increased at 28 days of life." (PMID 39768792, 2024). "Serum calcium and PTH increased in the following years (Ca 10,8 –11,8 and 12 mg/dl and PTH 732–1413 and 1753 pg/ml), with the onset of nephrocalcinosis." (PMID 36998475, 2023). "The clinical spectrum has been broadened to older children, teenagers and adults with nephrocalcinosis, renal stones and chronic fluctuating high serum and urine calcium with decreased serum PTH." (PMID 34721296, 2021). "Its phenotype also includes biochemical features of HVD (low PTH, high serum 1,25-(OH)2D, high urine calcium with renal stones and nephrocalcinosis) and normal to low FGF23 serum concentrations." (PMID 34721296, 2021). "Patient SOR171 is a 17-year-old male who was referred for evaluation of elevated serum PTH levels, low 25-hydroxyvitamin D levels, hypocalciuria, testicular microlithiasis and nephrocalcinosis." (PMID 32997713, 2020). "An abdominal ultrasound scan revealed bilateral nephrocalcinosis and bone biochemistry showed an elevated alkaline phosphatase, with a low PTH and serum calcium." (PMID 31435670, 2019). "Phosphorus therapy is associated with diarrhoea and is a stimulant to PTH secretion as well as FGF23 secretion; it is associated with nephrocalcinosis in treated patients with XLH and thus normalisation of serum phosphorus is not the target of therapy in XLH." (PMID 24594262, 2014). "Importantly, the two patients with the most marked drop in intact PTH developed mild nephrocalcinosis." (PMID 41035763, 2025). "While the drop of PTH concentrations correlated with the degree of increase of the urinary calcium/creatinine ratio and development of nephrocalcinosis, the small sample size may have masked the statistical significance of the 1,25(OH)2D levels." (PMID 41035763, 2025). "Additionally, blocking receptor-mediated endocytosis with a megalin inhibitor retained fetuin-A in the proximal tubule, protecting the kidneys from nephrocalcinosis in parathyroid hormone-treated rats." (PMID 38577269, 2024). "Additional studies, including plasma FGF23, PTH, iCa, and urinary calcium and phosphate measurements, are warranted to characterize whether these factors play a more important role in nephrocalcinosis." (PMID 35043997, 2022).